CRP (C-reactive protein)
Diseases named in the same sentence as CRP in open-access papers (continued):
Sharing a sentence is not in itself a finding about the gene and the disease.
cancer (continued). "Serum C-reactive protein (CRP) and albumin (ALB) were the most widely recognized indicators to predict prognosis in a variety of cancers, including ESCC." (PMID 35300627, 2022). "The modified Glasgow outcome scale (mGPS) and C-reactive protein-to-albumin ratio (CAR), are based on the two important acute phase proteins in SIR, namely C-reactive protein (CRP) and albumin, and are related to the prognosis of cancer patients." (PMID 35606690, 2022). "Findings from the European Prospective Investigation into Cancer and Nutrition (EPIC) Potsdam study indicate that MUNW participants had higher waist circumference, HbA1c and CRP than their metabolically healthy normal weight counterparts." (PMID 35564455, 2022). "Moreover, the GPS, a cumulative inflammation-based cancer-prognostic marker composed of serum elevation of CRP and decrease in albumin concentration, is likely to reflect host systemic inflammatory response and has been reported to be significant as a prognostic indicator in cancer-bearing patients." (PMID 36587139, 2022). "We also examined the correlation between IBS using CRP and/or albumin including PNI, CAR, mGPS and cancer prognosis." (PMID 36194563, 2022). "Deme and Telekes have also reviewed the value of elevated CRP, D-dimer, LDH, and decreased albumin for poor outcomes of cancer patients." (PMID 35173556, 2022). "CRP and ALB were the most widely recognized prognostic indicators in various cancers, including ESCC." (PMID 35300627, 2022). "This indicated that more attention should be paid to CRP-based inflammation biomarkers, such as LCR and CAR, when evaluating the inflammatory status of patients with cancer." (PMID 36517779, 2022). "In the context of cancer or cardiovascular diseases, white blood cell (WBC) populations and platelet counts, as well as C-reactive protein (CRP), have emerged as biomarkers." (PMID 36358351, 2022). "Furthermore, compound scores created by mixing albumin levels with positive acute reactants like CRP, as in the Glasgow prognostic score or globulin in albumin-globulin ratio, could also aid in prognosis estimations in patients with cancer and should be thoroughly investigated." (PMID 36533070, 2022). "Elevated levels of CRP have also been described in AIN related to other drugs, limiting its value as biomarker especially in cancer patients where systemic inflammation is frequently observed and influenced by tumor burden." (PMID 35755033, 2022). "The carcinoembryonic antigen (CEA), C-reactive protein (CRP), albumin, D-dimer, activated partial thromboplastin time (APTT), and R2 showed significant differentiation between benign and malignant tumors." (PMID 36359203, 2022). "The relationship between cancer and APP has been studied in human and veterinary medicine, with a particular focus on a positive correlation between CRP concentration and clinical manifestations of lymphoid neoplasia at the time of diagnosis." (PMID 36718344, 2022). "Specifically for cancer, a meta-analysis showed that a combination of RET and endurance training can reduce CRP levels." (PMID 35088134, 2022). "Other inflammatory markers for cancer diagnosis are erythrocyte sedimentation rate (ESR), C-reactive protein (CRP), procalcitonin (PCT), and D-dimer." (PMID 35978826, 2022). "The new cancer-specific scoring system consisted of six components: ECOG PS, SpO2, creatinine, total bilirubin, CRP, and lactate." (PMID 35236914, 2022). "P-CRP has increased sensitivity and accuracy for predicting the prognosis of malignant tumors because it fully combining the characteristics of PLT and CRP elevation that result in a poor prognosis." (PMID 36107592, 2022). "A significant increase (p < 0.01) in the levels of CRP and TNF-α was observed in both categories of cancer patients compared to the healthy individuals." (PMID 35692834, 2022).
cancer (continued). "These include: CDH1, MUC1, THBS4, and MSLN for PEs related to cancer; ADA2, CXCL10, and WARS for TB-PEs; CRP, S100A9, and VIM for parapneumonic PEs; and C9, LDHA, HPX, LDHB, and C3 for benign-PEs." (PMID 35197508, 2022). "Our multivariate survival analysis with different adjustment models showed that CRP, GNRI, ALI, and LCR all had significant survival predictive values in elderly patients with cancer." (PMID 35866083, 2022). "A study of 507 cancer patients in Germany, of which 60 developed a new VTE, found that those with VTE had higher circulating CRP levels in the 30 days prior to the VTE episode than those without any VTE in the follow up period." (PMID 36177015, 2022). "The authors found that CRP levels were significantly higher in patients with strong infiltration of CD8+ Foxp3+ cells, and cancer-specific survival was significantly worse in these patients than in patients with weak infiltration." (PMID 33635904, 2021). "The levels of CRP, Alb, and NLR are known prognostic indicators for patients with cancer, which was confirmed in the Cox analysis." (PMID 33757453, 2021). "In patients who developed cancer recurrence and had low SMA on staging CT TAP, significantly higher systemic levels of CRP, IL-6, VEGF, and expression of cell surface receptor CD14 were observed." (PMID 34459908, 2021). "When CRP was incorporated, the predictive accuracy of the UISS for predicting cancer specific mortality was increased by 3.7%." (PMID 34512646, 2021). "For systemic inflammation, serum levels of C-reactive protein (CRP) and neutrophil-to-lymphocyte ratio (NLR) derived from complete blood count have been well investigated as prognostic inflammatory markers in cancer patients." (PMID 34350956, 2021). "There are a few studies that have analyzed the kinetics of CRP, PCT and IL-6 in pediatric cancer patients with fever." (PMID 34828740, 2021). "Based on these statements, we selected three differentpeptidesas model ligands of various inflammatory-cancer biomarkers: tumornecrosis factor-α (TNF-α), vascular endothelial growthfactor (VEGF), and C-reactive protein (CRP)." (PMID 34114801, 2021). "Strikingly, both CRP and leukocytes were correlated with L3SMI and L3PMI, providing another explanation of how inflammation impacts the prognosis of cancer patients." (PMID 34771524, 2021). "System inflammation biomarkers, including CRP, NLR, and LMR, have been reported to evaluate the prognosis of human cancer." (PMID 34778081, 2021). "RDW is positively correlated with widely used plasma inflammatory markers, such as C-reactive protein (CRP) and blood sedimentation rate (ESR), and is considered to be an inflammatory marker in cancer patients." (PMID 33648470, 2021). "Several indicators based on common inflammatory factors, such as CRP, platelets and WBC, have prognostic value in various cancers." (PMID 34669737, 2021). "Several other predictive tools for cancer surgery prognosis have been developed, for example the prognostic nutritional index (PNI), the controlling nutritional status (CONUT) score, the CRP/Albumin ratio, and others." (PMID 34585050, 2021). "The neutrophil ratio, C-reactive protein (CRP), procalcitonin (PCT), white blood cells (WBCs), and IL-6 have been extensively studied as markers of long-term prognosis in many cancers." (PMID 34956932, 2021). "IL-6 also sustains cancer cell lysis through the activation of C-reactive protein (CRP) and its binding to the phospholipids of cancer cells, which, in turn, activates the component 1q of the complement system." (PMID 33923292, 2021). "C-reactive protein (CRP) is an acute-phase protein that is increased in infections, inflammatory conditions, and even cancers." (PMID 34868746, 2021). "Prior work has shown increases in circulating C-reactive protein (CRP) inflammatory cytokine, correlate to decreased CYP3A4 activity in advanced cancer patients." (PMID 33707475, 2021).
cancer (continued). "Thus, CRP may be directly involved in the progression and malignant properties of cancer cells." (PMID 33801202, 2021). "The modified Glasgow prognostic score (GPS) comprising serum CRP, albumin, as well as CAR measurements, indicates prognostic value in several cancers, including lung cancer." (PMID 33434414, 2021). "Therefore, many authors concluded that CRP may be a prognostic biomarker for many types of cancer." (PMID 33584142, 2021). "Plenty of research have explored the most commonly used indicators of inflammatory response, such as leukocytes, leukocyte subtypes, cytokines, CRP, LDH, ALP, and their potential effects on the prognosis of cancer patients." (PMID 35083140, 2021). "In the current study, patients with high NLRs (>15) had significantly more advanced cancer stages, and higher WBC and neutrophil counts and CRP levels, compared with the low NLR group." (PMID 33928250, 2021). "The PI incorporates the combination of CRP and WBC values, and was recently introduced as a simple marker in cancer patients with a potential prognostic value." (PMID 34143263, 2021). "This study aimed to examine the role of QLQ-C15-PAL scores and the inflammatory biomarkers CRP, Alb, and NLR for survival prediction to help avoid discomfort and inappropriate therapies in terminally ill patients with cancer." (PMID 33757453, 2021). "In addition to CRP, it has been shown that ESR has a prognostic value in treatment of some specific neoplastic diseases and it has been concluded that elevated ESR values may associate with poor prognosis in most of the cancers." (PMID 33584142, 2021). "In a retrospective review of 251 patients undergoing prostate biopsy for PSA > 4.0 ng/mL, there was a statistically significant difference in the natural log of CRP between BPH, ≤T2, and ≥T3 cancers." (PMID 34512646, 2021). "We performed an observational study to examine the role of QLQ-C15-PAL scores and the inflammatory biomarkers CRP, Alb, and NLR for survival prediction in terminally ill patients with cancer hospitalized in a palliative care unit." (PMID 33757453, 2021). "C-reactive protein (CRP) was initially found to be secreted by pathogens since its level was elevated in a variety of illnesses, including cancer." (PMID 33407080, 2021). "Our main objective was to analyze the usefulness of four different biomarkers (CRP, PCT, IL-6 and MR-proADM) as outcome predictors in febrile pediatric patients with cancer." (PMID 34828740, 2021). "We analyzed the prognostic impact (cancer-specific survival, i.e., from HNSCC) for CRP and for each of the 10 cytokine mediators." (PMID 33066437, 2020). "However, we need to mention that it is not clear whether CRP is a marker of cancer mortality or whether it may play a causative role." (PMID 31936330, 2020). "Finally, an MR study could be comparable to randomized clinical trials in providing a robust causal relationship if the genetic instruments are valid and not linked to cancer outcomes via alternative pathways other than those of the CRP phenotype." (PMID 33614510, 2020). "It is worldwide known that high levels of LDH characterize inflammatory patterns, together with CRP and ERS, which are highly detected in cancer patients." (PMID 33187551, 2020). "Oher configurations involving label-free paper-based immunosensors with immobilized capture antibodies have been reported for the detection of hormones, CRP, interferon (IFN-γ), cancer biomarkers, and cardiac biomarkers." (PMID 32660011, 2020). "We fit Cox proportional hazard models to examine the relationship between C-reactive protein (CRP) and fibrinogen with cancer mortality." (PMID 33243216, 2020). "As a test for the diseases, we measured the saliva levels of Abeta42 for AD, CRP for heart disease, and TNF for cancer." (PMID 32019214, 2020).
cancer (continued). "Many studies have reported the role of the systemic inflammation response, including C-reactive protein (CRP), albumin, neutrophil, and related variables, for predicting the prognosis of patients with various cancers, including mRCC." (PMID 32711491, 2020). "Moreover, the unique biological activity of mCRP or pCRP could help elaborate the clinical interpretations of CRP levels in patients suffering from cancer, thereby presenting CRP as a potential non-invasive technique to assess the severity of tumor development or progression." (PMID 33324413, 2020). "Potential biomarkers of systemic inflammation, including C-reactive protein, modified Glasgow prognostic score, NLR, PLR, and lymphocyte-to-monocyte ratio, correlated with cancer survival." (PMID 31768743, 2020). "The cytokine profile differed considerably also between these patients, and increased CRP and IL6 levels were independent markers for adverse prognosis (i.e., cancer-related death)." (PMID 32707721, 2020). "Recently, CRP and albumin with the Glasgow prognostic score (GPS) reported an independent prognostic value in patients with cancer." (PMID 32756384, 2020). "Consequently, serum levels of CRP may merely reflect the tumor load of cancer patients." (PMID 32982584, 2020). "More specifically, it provides a new perspective on the diagnostic and therapeutic value of the prototypic acute phase reactant, C-reactive protein (CRP), and cancer." (PMID 33324413, 2020). "Other cytokines related to cancer-mediated inflammatory process such as IL-8, TNF-α and CRP were also reduced by exercise training (18 m/min for 12 weeks, at 30 min for 5 days per week) in breast cancer mice." (PMID 33371214, 2020). "Combined measurement of CRP and ECPKA‐Ab levels in serum improves the sensitivity and accuracy of a diagnosis of cancer in dogs." (PMID 30411459, 2019). "The CRP level was also increased in the cancer group, and the NI, developed by regression analysis of both ECPKA‐Ab and CRP, had a higher AUROC than ECPKA‐Ab alone when both NI and ECPKA‐Ab had an AUROC >0.85." (PMID 30411459, 2019). "This concept is in part supported by two findings: i) CRP levels and NLR increase with advanced cancer stages while levels of AAT decrease, and ii) serum CRP and AAT, and NLR and AAT did not correlate." (PMID 31487965, 2019). "Traditionally, the level of serum C-reactive protein (CRP), an acute-phase marker of systemic inflammation synthesized by hepatocytes, has been a poor prognostic marker in patients with various cancers, including HCC." (PMID 30974843, 2019). "There are a variety of studies that have tested different inflammatory markers in cancer or neutropenic patients such as PCT, CRP, and IL-6." (PMID 30796468, 2019). "And C-reactive protein, adiponectin, and leptin play an important role in inflammatory environment that are related to SUA and cancer." (PMID 31885729, 2019). "The present systematic review shows low SMI and low SMD to be consistently associated with measures of systemic inflammatory response, including CRP, albumin, mGPS and NLR, in patients with cancer." (PMID 31487957, 2019). "Studies have demonstrated that the Glasgow prognostic score (GPS), which is a simple and useful score and obtained using C-reactive protein (CRP) and albumin values is a practical tool in the determination of prognosis in many cancer types." (PMID 31096693, 2019). "Based on the combination of serum CRP and serum albumin, the GPS is a well-established, cheap and readily available tool for prognostic assessment in cancer patients." (PMID 30535923, 2019). "In this context, several studies have reported on the apparent utility of measurement of serum C-reactive protein (CRP), a surrogate for IL-6, as a strategy to predict responsiveness of cancer patients to ICI-targeted immunotherapy." (PMID 31616428, 2019). "IMMUNEPOTENT CRP (I-CRP) is a DLE obtained from bovine spleen, with immunomodulatory but also cancer-cytotoxic activity." (PMID 31579619, 2019).
cancer (continued). "In those with advanced-stage (compared with early-stage) cancer, the albumin and HDL levels were significantly lower and the CRP level higher (p < 0.05)." (PMID 29941786, 2018). "Accordingly, inflammation-based prognostic indicators, such as the Glasgow prognostic score (GPS), C-reactive protein (CRP), and neutrophil-to-lymphocyte ratio (NLR), have been investigated in various cancers." (PMID 30539019, 2018). "C-reactive protein (CRP) is a prototype acute phase protein that was demonstrated to be produced in hepatocytes and regulated by growth factors in the malignant tumors such as IL-6." (PMID 29890986, 2018). "Biomarkers such as neutrophil-to-lymphocyte ratio (NLR), platelet-to-lymphocyte ratio (PLR), C-reactive protein (CRP), and cytokines have been suggested as measurable parameters of systemic inflammation and prognostic predictors in various cancers." (PMID 30532215, 2018). "Rising serum levels of CA19-9, CRP and ALP were apparent in BTC cases towards diagnosis, and all 3 markers were significantly (P < 0.05) different between BTC and non-cancer controls up to two years before diagnosis." (PMID 29707118, 2018). "For example, as a SIR marker, incorporating C-reactive protein (CRP), together with serum albumin, has a close relationship with outcomes in cancer patients." (PMID 29179480, 2017). "Accumulated evidence has demonstrated that the systemic inflammatory biomarkers including NLR, dNLR, PLR, CRP, GPS and mGPS represent independent prognostic factors for various types of cancer including RCC." (PMID 29299149, 2017). "Many inflammatory indicators that were explored to predict the prognosis in various cancers, such as neutrophil-to-lymphocyte ratio (NLR), PLR, C-reactive protein and so on, have greatly contributed to our understanding in pathogenesis of tumorous diseases." (PMID 28206965, 2017). "The aim of this systematic review was to study the effect of MBIs on specific biomarkers (cytokines, neuropeptides and C-reactive protein (CRP)) in both healthy subjects and cancer patients." (PMID 28231775, 2017). "Previous studies have shown that serum CRP and NLR are predictors of prognosis in several cancers, including EC." (PMID 29262582, 2017). "Recently, a novel inflammation-based prognostic score, the C-reactive protein/albumin ratio (CRP/Alb ratio, CAR) was reported as an independent prognostic marker for overall survival (OS) in several types of cancer." (PMID 27823974, 2017). "Several other acute-phase response proteins were also elevated towards diagnosis (e.g., HP, ORM1, ORM2, CRP, SERPINF2), presumably due to a host systemic inflammatory response—a known prognostic indicator in cancer patients." (PMID 29232830, 2017). "Various inflammatory factors, such as C-reactive protein (CRP), neutrophil to lymphocyte ratio(NLR), and platelet to lymphocyte ratio (PLR), have been investigated in various types of cancers." (PMID 29340113, 2017). "Certain systemic inflammation markers such as CRP, WBC, albumin, NLR, and platelet count have been confirmed to be poor prognostic factors in many cancer types." (PMID 28076369, 2017). "The combination of C-reactive protein and albumin, the Glasgow Prognostic Score (GPS), had independent prognostic value in patients with varying cancers, except for upper tract urothelial carcinoma (UTUC)." (PMID 29348903, 2017). "The prognostic and predictive values of markers of systemic inflammation such as serum C-reactive protein (CRP), which is included in the Glasgow Prognostic Score (GPS), are established for numerous malignant tumors." (PMID 28148894, 2017). "Here, we demonstrated stabilization of selected cancer biomarkers (LDH, CRP, PSA, MMP-7, and C3a) proving the technical feasibility of isothermal vitrification technology." (PMID 27068126, 2016). "Our results showed that CRP was higher in patients with infective effusions in keeping with its property as an acute-phase reactant, whereas serum LDH was higher in cancer patients." (PMID 26678281, 2016).